SLC31A1 (solute carrier family 31 member 1)
Diseases named in the same sentence as SLC31A1 in open-access papers (continued):
Sharing a sentence is not in itself a finding about the gene and the disease.
non-small cell lung carcinoma (5 papers, 2018 to 2025). A group of at least three distinct histological types of lung cancer, including non-small cell squamous cell carcinoma, adenocarcinoma, and large cell carcinoma. "Studies have shown that epigallocatechin-3-gallate (EGCG) can regulate SLC31A1 (CTR1, copper transporter 1) expression through upregulated lncRNA nuclear, which effects cisplatin sensitivity for the treatment of non-small cell lung cancer cells." (PMID 36915193, 2023). "In addition, SLC31A1 transports platinum drugs across the plasma membrane, and in patients with non-small cell lung cancer, SLC31A1 is a potential pharmacogenetic biomarker for clinical outcomes." (PMID 36973786, 2023).
thyroid cancer (5 papers, 2022 to 2025). "On the contrary, SLC31A1 was found to be higher in normal samples compared with tumor samples of cholangiocarcinoma, kidney, lung, prostate and thyroid cancers." (PMID 35996075, 2022).
atherosclerosis (4 papers, 2023 to 2025). A disease characterized by the build-up of fatty material and calcium deposition in the arterial wall resulting in partial or complete occlusion of the arterial lumen. "The area under curve (AUC) of SLC31A1, SLC31A2 and SOD1 for the diagnosis of atherosclerosis was 0.800, 0.779 and 0.798 respectively in the GSE28829 dataset, with SLC31A1 demonstrating good diagnostic performance." (PMID 37324184, 2023). "In GSE132561, GSE28829, and GSE120521, the ROC curves of FDX1, GLS, and SLC31A1 also verified that both had a high value for classification of the atherosclerosis stage." (PMID 37442861, 2023). "Three cuproptosis-related genes—SLC31A1, SLC31A2 and SOD1 were screened out as diagnostic biomarkers for atherosclerosis." (PMID 37324184, 2023). "Consistently, the atherosclerosis plaques showed significantly higher expression of SLC31A1, SLC31A2 and lower expression of SOD1 than the normal intimae." (PMID 37324184, 2023). "In the context of atherosclerosis, the upregulation of FDX1 and SLC31A1, along with the downregulation of glutaminase, was observed." (PMID 39290254, 2024). "The mechanistic roles of SLC31A1 and SLC31A2 in atherosclerosis and cardiovascular diseases need further experiments to confirm." (PMID 37324184, 2023). "In the training dataset GSE97210, SLC31A1, ATP7A, SLC31A2, UBE2D1, CP and FDX1 were highly expressed while LOXL2, COA6 and SOD1 were lowly expressed in the atherosclerosis group as showed in the bar charts." (PMID 37324184, 2023). "Furthermore, cuproptosis-related genes ferredoxin 1 (FDX1), solute carrier family 31 member 1 (SLC31A1), and glutaminase (GLS) are crucial in the onset and advancement of atherosclerosis." (PMID 40861271, 2025). "In summary, we identified three hub cuproptosis-related genes—SLC31A1, SLC31A2 and SOD1 and construct a possible ceRNA network and a transcription factor regulation network in the molecular mechanism of atherosclerosis, providing new insights into cuproptosis and atherosclerosis." (PMID 37324184, 2023). "Consequently, SLC31A1, SLC31A2 and SOD1 were regarded as three hub cuproptosis-related biomarkers in atherosclerosis." (PMID 37324184, 2023).
diabetes (4 papers, 2020 to 2024). "Huo S found that an excess of copper in patients with diabetes upregulated SLC31A1, leading to functional damage in cardiomyocytes in diabetic cardiomyopathy, which was possibly related to cuproptosis." (PMID 38904034, 2024). "To date, only the ATP7A protein is markedly downregulated in vessels isolated from T2DM patients and diabetic mice, whereas how the other copper transporters, ATP7B and SLC31A1, change in diabetes was uncertain." (PMID 36675183, 2023). "The excessive increase in AGEs and copper in diabetes induced the upregulation of copper importer SLC31A1 through ATF3/SPI1, thereby mediating the accumulation of copper in cardiomyocytes, disturbing copper homeostasis and promoting cuproptosis." (PMID 36675183, 2023). "Our findings showed, for the first time, that excessive AGEs and copper in diabetes upregulated ATF3/SPI1/SLC31A1 signaling, thereby disturbing copper homeostasis and promoting cuproptosis." (PMID 36675183, 2023). "Our data indicated that ATF3 and/or SPI1 might be upstream of SLC31A1 and regulate cuproptosis of cardiomyocytes in diabetes." (PMID 36675183, 2023). "In addition, we identified nine genes (CABIN1, CKS1B, C19orf60, SDR39U1, SLC31A1, DNAJA4, ZC3H8, OTUD3 and UBALD1) not previously associated with diabetes, but that are known to be involved in processes potentially linked to β-cell dysfunction, such as cell turnover, oxidative stress and ER stress." (PMID 33575641, 2020).
lung adenocarcinoma (4 papers, 2023). A carcinoma that arises from the lung and is characterized by the presence of malignant glandular epithelial cells. "A study has studied the crucial role of cuproptosis-related genes (CRGs) in lung adenocarcinoma and found that MTF1, SLC31A1, FDX1 and DLD were associated with the tumor microenvironment and immune responses in lung adenocarcinoma." (PMID 37380924, 2023).
psoriasis (4 papers, 2023 to 2025). An autoimmune condition characterized by red, well-delineated plaques with silvery scales that are usually on the extensor surfaces and scalp. "Notably, transcriptomic analyses have revealed the significant upregulation of cuproptosis-associated genes (MTF1, ATP7B, and SLC31A1) in psoriatic patients, while additional clinical research has demonstrated elevated serum copper levels in individuals with psoriasis." (PMID 40332377, 2025). "Then, through establishing an RF model, we used the three candidate genes as cuproptosis regulators (MTF1, ATP7B, and SLC31A1) to predict the occurrence of psoriasis." (PMID 37091865, 2023). "We established a genetic model for predicting psoriasis susceptibility based on three candidate cuproptosis-related genes (CRGs), MTF1, ATP7B, and SLC31A1, and found that patients can gain clinical benefits based on this model." (PMID 37091865, 2023). "The ROC curve prediction of the explored model genes (MTF1, ATP7B, and SLC31A1) showed that they could be used to reasonably predict the presence of psoriasis." (PMID 37091865, 2023). "Furthermore, it has been shown that SLC31A1 and MTF1 levels, as well as serum copper levels, were all elevated in psoriatic patients compared to controls, suggesting that SLC31A1 and MTF1 may be risk factors for psoriasis." (PMID 39652607, 2024). "To explore the correlation between key cuproptosis genes and drug sensitivity in psoriasis, we analyzed the sensitivity between ATP7B, SLC31A1, and MTF1 expression and drug sensitivity using the “pRRophetic” R package." (PMID 37091865, 2023). "We observed the expression of cuproptosis-related proteins, including ATP7B, SLC31A1, and MTF1, in psoriasis." (PMID 37091865, 2023). "The accumulation of intracellular copper leads to cell death, and the cuproptosis-related genes MTF1, ATP7B, and SLC31A1 are increasingly expressed in patients with psoriasis compared to patients without psoriasis." (PMID 38256115, 2024). "Co-expression of ATP7B, SLC31A1, and MTF1 suggests that these key cuproptosis genes may jointly influence psoriasis development." (PMID 37091865, 2023).
Sepsis (4 papers, 2024 to 2025). Sepsis is defined as life-threatening organ dysfunction caused by a dysregulated host response to infection. "The expression of SLC31A1, CD274, ATOX1, MTF1, UBE2D1, DLD, and VEGFA was found to be upregulated, while that of DLST, UBE2D2, COX11, DLAT, GLS, FDX1, and ULK2 were significantly downregulated in patients with sepsis-associated ALI." (PMID 38779731, 2025). "Furthermore, GSE236713 cohort was utilized to verify SLC31A1, MTF1, LIAS and LIPT1 level in sepsis." (PMID 39652607, 2024).
breast tumor (3 papers, 2022 to 2023). "Figures showed that the expression level of SLC31A1 in the breast tumor tissue was remarkably higher than that in the normal tissue." (PMID 35996075, 2022). "Furthermore, we examined the expression of SLC31A1 using real-time PCR in human breast samples, breast tumor cell lines (MCF-7 and BT-549), and human mammary epithelial cells (MCF10A)." (PMID 37275369, 2023). "Among them, the expression of the majority of genes was decreased in tumor samples except for four genes (ATP7B, SLC31A1, PDHB and CDKN2A), suggesting cuproptosis signaling was significantly downregulated in breast tumors." (PMID 36497253, 2022).
cardiomyopathy (3 papers, 2022 to 2023). A disease of the heart muscle or myocardium proper. "Recently, researchers have noticed the role of SLC31A1 in cardiomyopathy." (PMID 38085668, 2023). "In the future, the SLC31A1 gene and FDX1 gene are expected to be potential therapeutic targets for primary cardiomyopathy." (PMID 38085668, 2023).
diabetic cardiomyopathy (3 papers, 2023 to 2024). Diabetic cardiomyopathy is a disorder of the heart muscle in people with diabetes. "While the occurrence of diabetic cardiomyopathy is indeed linked to abnormal expression of SLC31A1 in cardiac myocytes, it remains unclear whether similar abnormalities exist in pancreatic β cells." (PMID 38904034, 2024). "One study reported that SLC31A1-related signaling pathways may be involved in the pathogenesis of diabetic cardiomyopathy." (PMID 38085668, 2023).
mesothelioma (3 papers, 2023). A usually malignant and aggressive neoplasm of the mesothelium which is often associated with exposure to asbestos. "Patients with high SLC31A1 expression have a shorter OS than those with low SLC31A1 expression in cases of ACC (p = 0.0025), BLCA (p = 0.0031), mesothelioma (MESO) (p = 3.5e−05), and skin cutaneous melanoma (SKCM) (p = 0.027)." (PMID 37853210, 2023).
Parkinson disease (3 papers, 2022 to 2023). A progressive degenerative disorder of the central nervous system characterized by loss of dopamine producing neurons in the substantia nigra and the presence of Lewy bodies in the substantia nigra and locus coeruleus. "Our results identified three characteristic cuprotosis-related genes ATP7A, SLC31A1, and DBT involved in the immune process of Parkinson’s disease." (PMID 36338988, 2022).
periodontitis (3 papers, 2023 to 2026). An acute or chronic inflammatory process that affects the tissues that surround and support the teeth. "We observed that the expression levels of the copper importer SLC31A1 and dihydrolipoamide S-acetyltransferase (DLAT) were positively correlated with bone loss in both human chronic apical periodontitis (CAP) tissues and mouse CAP models." (PMID 41629272, 2026).
brain cancer (2 papers, 2022). A primary or metastatic malignant neoplasm affecting the brain. "Brain cancers (GBM and LGG) were found to potentially have a higher copper metabolism-related cell death compared to normal brain tissue because their anti-cuproptosis gene ATP7B was downregulated with pro-cuproptosis genes SLC31A1, FDX1, DLAT, and LIAS upregulated in cancer tissues." (PMID 36276096, 2022).
lymph node metastasis (2 papers, 2025). "Univariate analysis showed that the degree of differentiation, lesion status, TNM stage, thyroid epidural invasion, lymph node metastasis, and serum SLC31A1 level were significantly prognostic factors (all P < 0.05)." (PMID 41216190, 2025). "Elevated serum SLC31A1 levels were significantly associated with poor prognosis, advanced TNM stages (III/IV), poor differentiation, thyroid exocapsular invasion, and lymph node metastasis." (PMID 41216190, 2025). "Clinicopathological parameters (age, sex, tumor diameter, differentiation, TNM stage, thyroid exocapsular invasion, lymph node metastasis) and serum SLC31A1 levels (measured via ELISA) were analyzed." (PMID 41216190, 2025).
pancreatic adenocarcinoma (2 papers, 2023). "Additionally, the expression of SLC31A1 in other malignancies, including colon adenocarcinoma (COAD), kidney chromophobe (KICH), pancreatic adenocarcinoma (PAAD), and rectal adenocarcinoma (REC), was insignificant." (PMID 37853210, 2023). "No significant change in SLC31A1 expression was found in some tumor types such as pancreatic adenocarcinoma (PAAD) and uterine carcinosarcoma (UCS)." (PMID 36973786, 2023).
pancreatic duct adenocarcinoma (2 papers, 2022 to 2024). "In pancreatic duct adenocarcinoma (PDAC), characterized by abnormal copper accumulation, targeting the copper transporter 1 (SLC31A1), or the treatment with a copper chelator, induce a dormancy-like response sustained by increased autophagy to resist cell death both in in vitro and in vivo models." (PMID 35158815, 2022).
triple-negative breast carcinoma (2 papers, 2023 to 2025). An invasive breast carcinoma which is negative for expression of estrogen receptor (ER), progesterone receptor (PR), and human epidermal growth factor receptor 2 (HER2). "Across molecular subtypes, SLC31A1 expression was highest in triple-negative breast cancer (TNBC) and significantly elevated in non-responders (n = 277) compared with responders (n = 196, P = 0.0021)." (PMID 41480020, 2025).
Alzheimer disease (1 paper, 2022). A progressive, neurodegenerative disease characterized by loss of function and death of nerve cells in several areas of the brain leading to loss of cognitive function such as memory and language. "Our results show that ATP7A is associated with steroid hormones, DBT is mainly associated with Alzheimer’s disease, and SLC31A1 is associated with axon guidance, calcium signaling pathways, and Long-term potentiation." (PMID 36338988, 2022).
chronic myeloid leukemia (1 paper, 2021). "It was reported that reduced ABCG2 and increased SLC22A1 mRNA expression are associated with imatinib response in chronic myeloid leukemia 54, and simultaneous high expressions of SLC31A1 and ABCG2 are associated with poor survival of HNSCC patients." (PMID 33531973, 2021).
colon carcinoma (1 paper, 2016). "Transcript‐level upregulation of SLC31A1,SCO1, and COX11 was also confirmed by the analysis of different colon carcinoma cell lines (Caco‐2, HT116, HT29) and cancer cell lines of different tissue origin (MCF7, PC3)." (PMID 27516958, 2016).
deafness (1 paper, 2018). An inherited or acquired condition characterized by the complete loss of the ability to hear from one or both ears. "We did not include the SNPs in the following genes: ACYP2 (coding for an acylphosphatase), SLC31A1 gene coding for the copper transport protein 1, SLC22A2 coding for the organic cation transport protein 2, megalin, TPMT and COMT and Mendelian deafness gene." (PMID 30112115, 2018).
Ductal Carcinoma (1 paper, 2024). "In pathological classification, the expression of SLC31A1 is higher in Infiltrating Ductal Carcinoma than Infiltrating Lobular Carcinoma and normal breast tissue." (PMID 39448672, 2024). "Regarding more specific typing, SLC31A1 is highly expressed in BC of HER2 + or Infiltrating Ductal Carcinoma (IDC)." (PMID 39448672, 2024).
metastasis (1 paper, 2025). The spread or migration of cancer cells from one part of the body (where they first appeared) to another. "These elevated copper levels correlate with clinical stage, tumor size, and lymph node metastasis in OSCC patients, accompanied by upregulation of SLC31A1." (PMID 40719074, 2025).
metastatic tumors (1 paper, 2021). "Further analysis showed increased SLC31A1 expression in patients with advanced/metastatic tumors (stage III–IV)." (PMID 34911956, 2021).
osteoporosis (1 paper, 2025). A condition of reduced bone mass, with decreased cortical thickness and a decrease in the number and size of the trabeculae of cancellous bone (but normal chemical composition), resulting in increased fracture incidence. "It showed that in osteoporosis patients, CP (P < 0.01), LIPT1 (P < 0.05), SLC25A3 (P < 0.001), and UBE2D3 (P < 0.01) were upregulated, while the expression levels of CDKN2A (P < 0.05), DBH (P < 0.01), DLST (P < 0.05), LOXL2 (P < 0.05), SLC31A1 (P < 0.05), and UBE2D1 (P < 0.01) were downregulated." (PMID 40980812, 2025).
papillary thyroid carcinoma (1 paper, 2025). "This study investigates the association between serum SLC31A1, a copper death-promoting factor, and clinicopathological features/prognosis in papillary thyroid carcinoma (PTC)." (PMID 41216190, 2025). "In summary, the high expression of SLC31A1 in thyroid papillary carcinoma is associated to poor clinicopathological features and prognosis, and SLC31A1 may become a potential therapeutic target for PTC." (PMID 41216190, 2025).
primary cardiomyopathy (1 paper, 2023). "The mRNA and protein levels of FDX1, MAP2K1 and SLC31A1 were significantly down-regulated during cuproptosis in cardiomyocytes, which was in line with the expression trends of the three kinds of primary cardiomyopathy groups in the GEO datasets." (PMID 38085668, 2023). "These four CRGs contained two core genes (FDX1 and SLC31A1) that regulate cuproptosis, suggesting that cuproptosis may be the common pathogenesis of the three kinds of primary cardiomyopathy." (PMID 38085668, 2023). "Therefore, we ultimately identified four genes as differential CRGs shared by the three kinds of primary cardiomyopathy: COA6, FDX1, MAP2K1, and SLC31A1." (PMID 38085668, 2023).
Thrombocytopenia (1 paper, 2018). A reduction in the number of circulating thrombocytes. "In this pharmacogenetic study, clinical outcomes such as severe thrombocytopenia hematological toxicity and overall survival of NSCLC patients with platinum-based chemotherapy were associated with linked non-coding variants of SLC31A1 gene that codes the transporter for platinum agent intake." (PMID 29844858, 2018).
uveal melanoma (1 paper, 2023). A melanoma derived from melanocytes of the uveal tract. "Moreover, in uveal melanoma (UM), SLC31A1 expression is negatively correlated with most functions, including DNA repair, DNA damage, and apoptosis." (PMID 37853210, 2023).
viral myocarditis (1 paper, 2024). Myocarditis that is caused by an infection with a viral agent. "Overexpression of DBT and SLC31A1 is involved in Leishmania infection, glycan biosynthesis, and viral myocarditis." (PMID 39315155, 2024).